APOB (apolipoprotein B)
Diseases named in the same sentence as APOB in open-access papers (continued):
Sharing a sentence is not in itself a finding about the gene and the disease.
liver disease (18 papers, 2015 to 2026). "Briefly, rare mutations in apolipoprotein B (APOB) predispose to familial hypobetalipoproteinaemia and progressive liver disease due to impaired triglycerides assembly into very low‐density lipoproteins and failure to secrete triglycerides from the liver." (PMID 33102799, 2020). "In particular, the identification of mutations that cause inhibition of lipid secretion, such as those in TM6SF2 and APOB, may help to select patients with high risk of liver disease, but strongly protect against cardiovascular complications." (PMID 31375010, 2019). "The deleterious effect on liver damage of the impaired ability to secrete triglycerides in VLDL is also supported by the association between progressive liver disease and rare apolipoprotein B (APOB) and microsomal triglyceride transfer protein (MTTP) mutations directly causing VLDL retention." (PMID 26273621, 2015). "ApoB/ApoA1 ratio in the serum of individuals with various forms of liver diseases and healthy people varied." (PMID 38744926, 2024). "Rare variants in Apolipoprotein B (APOB) have been associated with hypo-betalipoproteinemia, characterized by severe hepatic fat accumulation, with frequent progression to advanced liver disease and HCC." (PMID 31375010, 2019). "Here, we show GP73, a Golgi protein upregulated in livers from patients with a variety of liver diseases, exhibits Rab GTPase-activating protein (GAP) activity regulating ApoB export." (PMID 34853313, 2021). "Only apoB, very large and very small TRLP, LDLP, and large HDLP were not significantly different between the pre-transplant cirrhotic patients and OLT recipients after adjustment for age, sex, and primary liver disease aetiology." (PMID 35268313, 2022).
coronary artery stenosis (17 papers, 2011 to 2026). "A study indicated an association between the CELSR2 T/T risk genotype, elevated ApoE and ApoB levels, and coronary artery stenosis extension." (PMID 40076958, 2025). "The mutation at PCSK6 rs1531817 increased the ApoA1/ApoB ratio, which in turn protected against severe coronary stenosis." (PMID 39039525, 2024). "Our study also found that lipid ratios such as the ApoB/ApoA-1 ratio (BAR) were closely associated with the degree of coronary artery stenosis and might have a potential predictive value for CHD severity." (PMID 40129766, 2025). "This study found that RC, along with various lipid ratios (TG/HDL-C, TC/HDL-C, LDL-C/HDL-C, and ApoB/ApoA) played a critical role in assessing the severity of coronary artery stenosis in patients with CHD." (PMID 40129766, 2025). "In the bivariate logistic regression, each standard deviation (SD) increase in apoB corresponded to a 2.386-fold increase in the odds of significant coronary stenosis." (PMID 41374382, 2025). "Patients with the PCSK6 CA + AA genotype have milder coronary stenosis and a better long-term prognosis; according to the mediation model, ApoA1/ApoB and TC/HDL partially mediate." (PMID 39039525, 2024). "To investigate the relationship between ApoB/A1 and the severity of coronary artery stenosis, we utilized simple linear regression analysis." (PMID 34961824, 2021). "According to the specific patient groups who would be diagnosed or treated by coronary angiography, we elucidated the relationship between ApoB/A1 and the severity of coronary artery stenosis." (PMID 34961824, 2021). "In our study, we have illustrated the relationship of ApoB/A1 and severity of coronary artery stenosis in detail as compared to other work previously." (PMID 34961824, 2021). "PMI patients with the PCSK6 CA + AA genotype have milder coronary stenosis, partially because they have higher ApoA1/ApoB levels; patients with the PCSK6 CA + AA genotype have a better long-term prognosis, partially because they have lower TC/HDL levels and are less likely to have TVD." (PMID 39039525, 2024). "Moreover, linear regression analysis indicated that the ApoB/A1 was significantly positively correlated with the Gensini score, an indicator of the severity of coronary artery stenosis." (PMID 34961824, 2021). "ApoB/A1 is highly associated with the presence and severity of coronary artery stenosis in patients with CAD but not in non-CAD patients." (PMID 34961824, 2021). "We further explored whether ApoB/A1 contributed to the severity of coronary artery stenosis in CAD group." (PMID 34961824, 2021). "The relationships between ApoB/A1 and severity of coronary artery stenosis were evaluated." (PMID 34961824, 2021). "In a large population without a previous history of CVD, serum apoB/A-I ratios were significantly associated with coronary artery stenosis, as determined using multidetector computed tomography." (PMID 28957410, 2017). "Moreover, ApoB/A1 is highly and independently associated with the severity of coronary artery stenosis of CAD patients but not in non-CAD patients." (PMID 34961824, 2021). "To further analyze the correlation between ApoB level, LDL-C level and the degree of coronary artery stenosis, we performed a generalized linear model analysis." (PMID 41030852, 2025). "Although the roles of the apolipoprotein B/A1 ratio (ApoB/A1) were originally thought to be atherosclerotic, few studies have focused on the specific relationship between ApoB/A1 and severity of coronary artery stenosis with or without the presence of CAD." (PMID 34961824, 2021). "However, in their study, apoB alone did not offer any additional predictive power for coronary stenosis over LDL-C." (PMID 37629496, 2023). "Notably, only the ApoB/A1 was found to be significantly positively correlated with the severity of coronary artery stenosis in CAD patients (95% CI 0.103 to 0.181, p < 0.001), not in the group of non-CAD patients (95% CI −0.007 to 0.136, p = 0.079)." (PMID 34961824, 2021).
coronary artery stenosis (continued). "However, it remains unclear whether ApoB/A1 correlated with the severity of coronary artery stenosis, and the difference between CAD and non-CAD groups was still vague." (PMID 34961824, 2021).
type 1 diabetes (17 papers, 2009 to 2026). "A study on adolescents with type 1 diabetes had shown that elevated apoB was significantly associated with increased arterial stiffness, especially in those with borderline LDL-C (2.59–3.34 mmol/L), and apoB in addition to LDL-C might help stratify the CVD risk." (PMID 34325713, 2021). "Apolipoprotein A1 was significantly higher in patients with type 1 diabetes – an observation in line with previous reports, and the Apolipoprotein B/Apolipoprotein A1 quotient was lower." (PMID 38084202, 2023). "Compared to nondiabetic controls, apolipoprotein A1 was significantly higher, and apolipoprotein B and the ratio Apolipoprotein B/Apolipoprotein A1 were significantly lower in patients with type 1 diabetes." (PMID 38084202, 2023). "Similarly, plasma samples of patients with non-insulin-dependent diabetes displayed elevated levels of IDL ApoB, which are potentially atherogenic." (PMID 38895187, 2024). "Indeed, cardiac myocytes secrete apoB-containing lipoproteins and cardiac triglyceride accumulation is attenuated in apoB-overexpressing transgenic mice with streptozotocin-induced type 1 diabetes, lipoprotein lipase overexpressing mice, and LCAD-deficient mice." (PMID 19390571, 2009). "In placental sections from women with and without type 1 diabetes, immunostaining of apolipoprotein B100 (ApoB, a marker of LDL), Ox-LDL and lipoxidation product 4-hydroxynonenal was performed." (PMID 33504507, 2021).
atrial fibrillation (16 papers, 2014 to 2026). A disorder characterized by an electrocardiographic finding of a supraventricular arrhythmia characterized by the replacement of consistent P waves by rapid oscillations or fibrillatory waves that vary in size, shape and timing and are accompanied by an irregular ventricular response. "The second most pleiotropic SNP (rs1458038) is mapped to the PRDM8 gene that is implicated in affecting blood pressure, atrial fibrillation, apolipoprotein B levels, LDL cholesterol levels." (PMID 36579561, 2022). "The relationship between apolipoprotein B (APOB) and atrial fibrillation (AF) is less well-known." (PMID 35688870, 2022). "Also, the genetically predicted the ApoB/ApoA1 ratio had a significant positive association with the occurrence rates of PAD, non-rheumatic valve diseases, atrial fibrillation and atrial flutter (PFDR<0.05 in at least three MR methods in the four methods)." (PMID 38310324, 2024).
Cognitive impairment (16 papers, 2011 to 2026). Abnormal cognition is characterized by deficits in thinking, reasoning, or remembering. "The association between serum ApoA1 or ApoB levels and cognitive impairment in patients with schizophrenia were regulated by the existence of ApoE rs429358 polymorphism." (PMID 34135129, 2021). "Several animal studies also have shown a significant association between ApoB and cognitive deficits." (PMID 28054633, 2017). "Only the ApoB was negatively associated with cognitive impairment in male patients." (PMID 36506447, 2022). "In addition, increased ApoB was associated with decreased cerebrospinal fluid p-tau and t-tau in participants with subjective cognitive decline, which can explain why ApoB was associated with lower odds of cognitive impairment." (PMID 36506447, 2022). "Additionally, we aim to explore whether the ApoB/ApoA-I ratio is associated with domain-specific cognitive deficits, providing further insights into the underlying mechanisms of PSCI." (PMID 37960323, 2023). "MCI, mild cognitive impairment; TG, triglyceride; Cer, ceramide; ApoB, apolipoprotein B; PAFAH, platelet-activating factor acetylhydrolase." (PMID 36112688, 2022). "A negative association was also found between ApoB levels and cognitive impairment (Model 1, p for trend = 0.004), but the association was not significant after adjusting for confounders (p for trend = 0.791)." (PMID 37692108, 2023). "Second, owing to the cross-sectional study design, the causality between ApoE rs429358, ApoA1 and ApoB levels, and cognition impairment in patients with schizophrenia was not directly revealed." (PMID 34135129, 2021). "We hypothesized that the ApoE polymorphism rs429358 would lead to the changes in ApoA1 and ApoB levels, thereby playing a role in cognitive impairment in schizophrenia." (PMID 34135129, 2021). "As the elevated ApoB/ApoA1 ratio may lead to large RN volume, the increased lesion volume may contribute to cognition impairment." (PMID 32017458, 2020). "Accumulating evidence has shown that apolipoprotein B (ApoB) levels, which are responsible for inducing neurodegeneration, may be involved in cognitive deficits." (PMID 28054633, 2017). "A previous study claimed that serum levels of liver biomarkers were correlated with psychiatric disorders or cognitive deficits, and Amyloid PET, CSF amyloid, Plasma amyloid, CSF phosphorylated tau, Apolipoprotein-B might influence the severity of cognitive deficits." (PMID 37821909, 2023). "Data demonstrated that only serum ApoB activity, rather than serum globulin levels, may be associated with cognitive deficits." (PMID 37670828, 2023). "Therefore, we conducted this study to explore the relationship between cognitive impairment and ApoA1 and ApoB levels in patients with schizophrenia, because it may be altered by the ApoE polymorphism rs429358." (PMID 34135129, 2021). "Patients with cognitive impairment had lower concentrations of LDL-C, TG, and ApoB, and higher concentrations of HDL-C than patients with normal cognition." (PMID 36506447, 2022). "The metabolites, including sphinganine and 3-dehydrosphinganine, decreased in the cognitive impairment group, and positively correlated with TC, NHDL-C, LDL-C, and ApoB." (PMID 36506447, 2022). "Diastolic blood pressure (DBP), body mass index (BMI), TC, LDL‐C, and ApoB levels were lower in participants with cognitive impairment than in those without cognitive impairment (ps < 0.05)." (PMID 37692108, 2023). "Serum apolipoprotein A1 is associated with cognitive impairment in patients with T2DM, but not TC, TG, HDL-C, LDL-C, and apolipoprotein B, indicating that increased serum apolipoprotein A1 may be a risk factor of cognitive impairment in patients with T2DM." (PMID 38167163, 2024). "Furthermore, including lipid profile as covariates did not affect the ability of ApoA1, ApoA2 and ApoH levels and ApoB/ApoA1 ratio to predict cognitive impairment." (PMID 22701550, 2012).
Cognitive impairment (continued). "Moreover, since the increase in TC, FC, EC, LDL, apoB and TG, plus the reduction in HDL-cholesterol, are predictors of cognitive impairment, they might be proposed as translational biomarkers for MCI and/or AD." (PMID 21829488, 2011).
carotid atherosclerosis (15 papers, 2012 to 2025). A thickening and loss of elasticity of the walls of carotid arteries that occur with formation of atherosclerotic plaques. "Apolipoprotein B was shown to be a more accurate risk predictor for developing atherosclerotic heart disease than low-density lipoprotein cholesterol." (PMID 36506940, 2022). "Recently, it has been demonstrated that ApoB/ApoA1 ratio is independently associated with carotid atherosclerosis in T2DM patients with controlled LDL-c levels." (PMID 32505210, 2020). "The mean apoB/apoAΙ ratios were significantly higher among the participants with carotid atherosclerosis (0.91 ± 0.02 in men and 0.85 ± 0.03 in women) compared to participants without carotid atherosclerosis (0.85 ± 0.01 in men and 0.75 ± 0.01 in women) (P < 0.05)." (PMID 25885111, 2015). "To compare the predictive values of the different ratios in predicting carotid atherosclerosis, we analysed the ROC curves of the two ratios (apoB/apoAΙ and non-HDL-C/HDL-C)." (PMID 25885111, 2015). "In the present study, we examined the relationship among carotid atherosclerosis, the apoB/apoAΙ ratio, and the non-HDL-C/HDL-C ratio, as well as conventional lipids, IR, and C reactive protein (CRP), among Chinese individuals with MetS." (PMID 25885111, 2015). "The Spearman correlation coefficients between carotid atherosclerosis and the apoB/apoAΙ ratio and the non-HDL-C/HDL-C ratio were higher in women compared to men." (PMID 25885111, 2015). "Several studies have demonstrated that the apoB/apoAΙ ratio and the non-HDL-C/HDL-C ratio may be used to predict the risk of carotid atherosclerosis." (PMID 25885111, 2015). "However, none of these previous studies compared the ratio of apoB/apoAΙ with the ratio of non-HDL-C/HDL-C relative to carotid atherosclerosis among Chinese individuals with MetS." (PMID 25885111, 2015). "We noted that the ratios of apoB/apoAΙ and non-HDL-C/HDL-C each positively correlated with carotid atherosclerosis among Chinese individuals with MetS, particularly women." (PMID 25885111, 2015). "Both the apoB/apoAΙ ratio and the non-HDL-C/HDL-C ratio positively correlated with carotid atherosclerosis among Chinese individuals with MetS, particularly among women." (PMID 25885111, 2015). "We aimed to determine the relationship between the apoB/apoAΙ ratio and the non-HDL-C/HDL-C ratio and carotid atherosclerosis among Chinese individuals with MetS." (PMID 25885111, 2015). "Several studies have used both the apolipoprotein B (apoB)/apolipoprotein AΙ (apoAΙ) ratio and the non-HDL-C/HDL-C ratio to estimate the likelihood of having carotid atherosclerosis." (PMID 25885111, 2015). "Both the apoB/apoAΙ ratio and the non-HDL-C/HDL-C ratio positively correlated with carotid atherosclerosis." (PMID 25885111, 2015). "However, among individuals with MetS, direct comparative data regarding the utility of the apoB/apoAΙ ratio and the non-HDL-C/HDL-C ratio to diagnose carotid atherosclerosis are scarce, particularly in Chinese populations." (PMID 25885111, 2015).
dementia (15 papers, 2016 to 2026). Loss of intellectual abilities interfering with an individual's social and occupational functions. "We found both ApoB and the ApoB/ApoA1 ratio to be associated with higher risk of dementia only in women, and only when the follow‐up was over 20 years." (PMID 37243914, 2023). "Compared to respective lowest quarters, highest quarter of ApoA was associated with lower dementia risk (HR, [95% confidence interval (95% CI)]: 0·77 [0·69, 0·86]) while the highest quarter of ApoB was associated with greater risk (HR, 1·12 [1·01, 1·24])." (PMID 36247924, 2022). "For LDL/ApoB ratio, the highest quarter (1·39 to 2·72) was associated with a lower risk of dementia when compared with the lowest quarter (0·264 to 1·27) (HR, 0·85 [0·76, 0·94]) (p for trend=0.002)." (PMID 36247924, 2022). "Our study found associations between apolipoproteins and the risk of dementia: a higher level of ApoA was associated with a lower risk of dementia, and the association between ApoB and the risk of dementia was U-shaped." (PMID 36247924, 2022). "A higher LDL/ApoB ratio was associated with a lower risk of dementia (HR, 0·92 [0·89, 0·96], per SD)." (PMID 36247924, 2022). "The relationships between ApoB quarters and the risk of dementia were U-shaped, with the highest quarter (1·18 to 2·0 g/L) associated with a higher risk of dementia than the lowest quarter (0·4 to 0·86 g/L) (HR, 1·12 [1·01, 1·24]) (p for trend=0·043)." (PMID 36247924, 2022). "For the ratios, higher HDL/ApoA and ApoB/ApoA ratio were associated with a greater risk of dementia, while higher LDL/ApoB ratio was associated with a lower risk of dementia." (PMID 36247924, 2022). "In addition, elevated citrate has been linked to higher risk of AD and other dementias, and higher apolipoprotein B by apolipoprotein A-I correlates with lower educational level." (PMID 41146645, 2026). "While it may be due to reverse causation, after excluding the people diagnosed with dementia or that died within the first five years, the U-shaped association remained robust for ApoB and dementia." (PMID 36247924, 2022). "For ApoB/ApoA ratio, when compared with the lowest quarter (1·69 to 5·45), the highest quarter (8·12 to 37·1) was associated with a greater risk of dementia (HR, 1·23 [1·11, 1·37]) (p for trend=0·001), and with a higher value indicated a greater risk of dementia (HR, 1·09 [1·05, 1·13], per SD)." (PMID 36247924, 2022). "Moreover, we cannot rule out that in diseases reducing BBB integrity, such as LOAD, LDL may be filtrated through the damaged endothelium, explaining the association of apoB concentration with increased risk of dementia." (PMID 36231005, 2022). "Consistent with this understanding, existing literature has underscored that elevated ApoB, diminished ApoA-I, and an increased ApoB/ApoA-I ratio are robust indicators of both cardiovascular diseases and dementia in the general population." (PMID 37960323, 2023). "Higher HDL/ApoA and ApoB/ApoA, were associated with greater risk of dementia (HR, 1·12 [1·00, 1·25], per standard deviation (SD), 1.23 [1·11, 1·37], per SD, respectively), LDL/ApoB was inversely associated (HR, 0·85 [0·76, 0·94], per SD." (PMID 36247924, 2022). "In the dementia group, there was a positive correlation between the ratio of apoprotein B (apoB)/low density lipoprotein (LDL) and the Mini Mental State Examination (MMSE) score (R = 0.411, P = 0.011)." (PMID 27887584, 2016). "The present study showed two interesting findings: 1) Lipid levels of the dementia patients were lower than those of the infarction patients in our study; 2) The apoB/LDL ratio appeared to be positively related to the MMSE score in the dementia patients." (PMID 27887584, 2016). "However, some studies have not found associations of apolipoprotein A-I, citrate, or apolipoprotein B by apolipoprotein A-I with dementias or cognitive abilities." (PMID 41146645, 2026).